ZNF845 (zinc finger protein 845)
Description:
May be involved in transcriptional regulation.
Tractability: PROTAC: UniProt records ubiquitination sites on it; ubiquitination databases record sites on it.
Gene: Protein-coding gene on chromosome 19 (53,333,749 to 53,356,906, forward strand). Ensembl gene ENSG00000213799.
Subcellular location: Nucleus
Gene Ontology:
Molecular function: transcription cis-regulatory region binding; sequence-specific DNA binding
Biological process: negative regulation of transcription by RNA polymerase II; regulation of DNA-templated transcription
Cellular component: nucleus
Genetic constraint (gnomAD): Loss-of-function variants: 59 observed, 77.76 expected, observed/expected ratio (o/e) 0.76, 90% interval 0.61 to 0.94. The upper end of that interval is the gene's LOEUF score, 0.94, which puts it in group 3 of 6, group 1 being the genes least tolerant of losing a copy. Missense variants: 1,045 observed, 1,199 expected, observed/expected ratio (o/e) 0.87, 90% interval 0.83 to 0.92. Synonymous variants: 361 observed, 384.07 expected, observed/expected ratio (o/e) 0.94, 90% interval 0.86 to 1.02.
Homologues: Orthologues: chimpanzee ZNF845 (99% identical), mouse Zfp748 (41% identical), mouse Zfp712 (41% identical), rat Zfp712 (40% identical), rat Zfp748 (40% identical), rat Zfp729 (40% identical), rat Zfp729b (40% identical), mouse Zfp729a (40% identical), mouse Zfp729b (39% identical), mouse Zfp458 (39% identical), rat Zfp458 (38% identical), mouse Zfp759 (35% identical), and 1 more. Paralogues in human: ZNF160 (44% identical), ZNF347 (39% identical), ZNF665 (37% identical), ZNF91 (37% identical), ZNF729 (35% identical), ZNF208 (35% identical), ZNF107 (35% identical), ZNF99 (34% identical), ZNF420 (34% identical), ZNF184 (32% identical), ZNF84 (32% identical), ZNF594 (30% identical), and 24 more.
Diseases named in the same sentence as ZNF845 in open-access papers:
ZNF845 is named in the same sentence as 3 diseases in open-access papers, as found by Europe PMC text mining. Sharing a sentence is not in itself a finding about the gene and the disease. The quoted sentences say what the papers report.
tumor (2 papers, 2022 to 2023). "The patient-based analysis identified one additional significant gene, ZNF845 (Padj = 2.6 × 10−2), whereas the tumor-based analysis identified four, TNRC6B (Padj = 2.9 × 10−4), ZNF780B (Padj = 4.2 × 10−2), RPP30 (Padj = 6.4 × 10−2), and CASQ1 (Padj = 8.7 × 10−2)." (PMID 35922826, 2022).
ZNF845 also shares sentences with these, for which no sentence is quoted: melanoma (1 paper); progressive supranuclear palsy (1).